STOML1 (stomatin like 1)
Description:
May play a role in cholesterol transfer to late endosomes. May play a role in modulating membrane acid-sensing ion channels. Can specifically inhibit proton-gated current of ASIC1 isoform 1. Can increase inactivation speed of ASIC3. May be involved in regulation of proton sensing in dorsal root ganglions (By similarity). May play a role in protecting FBXW7 isoform 3 from degradation.
Synonyms: SLP-1; STORP; hUNC-24; FLJ36370
Tractability: Antibody: UniProt places it where antibodies can reach, with medium confidence; UniProt predicts a signal peptide or a membrane-spanning region; its Gene Ontology location is reachable by antibodies, with medium confidence. PROTAC: ubiquitination databases record sites on it; its protein half-life has been measured.
Gene: Protein-coding gene on chromosome 15 (73,978,926 to 73,994,622, reverse strand). Ensembl gene ENSG00000067221.
Subcellular location: Membrane; Late endosome membrane; Membrane raft; Cell membrane; Cytoplasmic vesicle
Subcellular location (Human Protein Atlas): Vesicles
Gene Ontology:
Molecular function: protein binding; ion channel inhibitor activity
Cellular component: late endosome membrane; membrane raft; cytoplasmic vesicle; plasma membrane; membrane
Genetic constraint (gnomAD): Loss-of-function variants: 27 observed, 34.25 expected, observed/expected ratio (o/e) 0.79, 90% interval 0.58 to 1.09. The upper end of that interval is the gene's LOEUF score, 1.09, which puts it in group 4 of 6, group 1 being the genes least tolerant of losing a copy. Missense variants: 451 observed, 525.03 expected, observed/expected ratio (o/e) 0.86, 90% interval 0.79 to 0.93. Synonymous variants: 219 observed, 226 expected, observed/expected ratio (o/e) 0.97, 90% interval 0.87 to 1.08.
Homologues: Orthologues: chimpanzee STOML1 (99% identical), macaque STOML1 (98% identical), dog STOML1 (92% identical), rat Stoml1 (90% identical), mouse Stoml1 (89% identical), guinea pig STOML1 (86% identical), pig STOML1 (79% identical), zebrafish stoml1 (47% identical), tropical clawed frog stoml1 (41% identical), Caenorhabditis elegans unc-24 (24% identical). Paralogues in human: STOM (22% identical), STOML3 (22% identical), NPHS2 (20% identical), STOML2 (16% identical).
Diseases named in the same sentence as STOML1 in open-access papers:
STOML1 is named in the same sentence as 3 diseases in open-access papers, as found by Europe PMC text mining. Sharing a sentence is not in itself a finding about the gene and the disease. The quoted sentences say what the papers report.
pancreatic cancer (1 paper, 2025). "GFPT2 is also implicated in stomatin-like protein 1 (STOML1)-driven liver metastasis of pancreatic cancer." (PMID 40830088, 2025).
Stroke (1 paper, 2025). Sudden impairment of blood flow to a part of the brain due to occlusion or rupture of an artery to the brain. "Shared DEGs between AIS and CIS, including genes such as KIF5B, C4orf3, APMAP, and STOML1, may reflect common molecular signatures associated with stroke across different clinical stages." (PMID 41356252, 2025). "Regional MSN differences were associated with cortical transcriptional gradients, identifying key stroke-related genes (e.g., KIF5B, C4orf3, APMAP, STOML1)." (PMID 41356252, 2025).
STOML1 also shares sentences with these, for which no sentence is quoted: tumor (1 paper).